RAD51D (RAD51 paralog D)
Diseases named in the same sentence as RAD51D in open-access papers (continued):
Sharing a sentence is not in itself a finding about the gene and the disease.
ovarian carcinoma (continued). "Other mutations were uniquely enriched in HRD+ predicted cases of breast and ovarian cancers (BARD1, BRIP1, MRE11, RAD51D) and cancer cohorts outside breast and ovarian cancer (RAD51B), suggesting additional unique drivers of HRD that may be cancer-cohort specific." (PMID 35643464, 2022). "In addition to 13.7% of deleterious germline BRCA1/BRCA2 carriers, we identified 7.4% additional patients with pathogenic germline variants in other genes predisposing for ovarian cancer, namely RAD51C, RAD51D, and MSH6, representing 35% of all pathogenic germline variants." (PMID 33008098, 2020). "Also mutations in RAD51C have not been found to increase the risk of breast cancer and mutations in RAD51D have been associated with high risk of ovarian cancer but not with breast cancer." (PMID 29566657, 2018). "BOADICEA V5’s newest version includes the effects of pathogenic variants (PVs), not restricted to BRCA1 and BRCA2 genes but also in PALB2, CHEK2, ATM, and BARD1 for the breast cancer model and RAD51D, RAD51C, and BRIP1 for the ovarian cancer model." (PMID 39590369, 2024). "The current panel of genes with strong evidence for use in clinical practice include PALB2, CHEK2, ATM, RAD51C and RAD51D with additional genes such as BARD1 (breast cancer) and BRIP1 (ovarian cancer) continuing to emerge." (PMID 39107016, 2024). "In the course of our study, the ovarian cancer gene panel consisted of the five core genes (BRCA1, BRCA2, BRIP1, RAD51C and RAD51D), and it is likely that the gene panel will be expanded with other cancer genes, such as PALB2, in the near future." (PMID 34617209, 2022). "The prevalence of a personal or family history of ovarian cancer among women with PVs in BRIP1, RAD51C, or RAD51D was similar to that observed for women with PVs in BRCA1 or BRCA2 in this cohort." (PMID 33926482, 2021). "Overall, testing for moderate- or high-penetrance BRCA1/2, RAD51C, RAD51D, BRIP1, and mismatch repair genes for the patients with epithelial ovarian cancer is recommended." (PMID 34207568, 2021). "Similar to BRCA2, the median age of ovarian cancer diagnosis was older for women with a PV in BRIP1 (65 years), RAD51C (62 years), or RAD51D (57 years)." (PMID 33926482, 2021). "The median age at ovarian cancer diagnosis of women with a PV in BRIP1, RAD51C, or RAD51D was much older and more than three quarters of women with a PV in one of these three genes and a history of ovarian cancer was diagnosed after the age of 50." (PMID 33926482, 2021). "A personal history of ovarian cancer was most common among women with a PV in RAD51C (17.4%, 149/855) or RAD51D (16.3%, 74/455)." (PMID 33926482, 2021). "The age at ovarian cancer diagnosis was older for women with PVs in BRIP1, RAD51C, or RAD51D, suggesting that it is safe to delay RRSO until age 45–50 in RAD51D PV carriers and possibly until age 50–55 in BRIP and RAD51C PV carriers." (PMID 33926482, 2021). "A number of the RAD51 mediators have now been added to the more comprehensive breast and ovarian cancer screening panels (i.e., PALB2, RAD51C, RAD51D, XRCC2)." (PMID 30551670, 2018). "In this study, we analysed the five RAD51 paralogs (RAD51B, RAD51C, RAD51D, XRCC2, XRCC3) in 142 unrelated patients with breast and/or ovarian cancer to estimate their contribution to breast and ovarian cancer predisposition." (PMID 24139550, 2013). "In ovarian cancer, pathogenic variants in BRCA1, BRCA2, RAD51C, RAD51D, and PALB2 predict PARP inhibitor efficacy, but this has not been established for other HRR-related genes." (PMID 40069561, 2025). "Notably, in patients with ovarian cancer, a significant number of PVs were identified in the moderate penetrance RAD51 genes; RAD51C (1.5%) and RAD51D (1%), followed by the MMR and ATM genes." (PMID 34326862, 2021). "This suggests that panel testing may help guide treatment selection for women with ovarian cancer by identifying PVs in BRIP1, RAD51C, or RAD51D." (PMID 33926482, 2021).
ovarian carcinoma (continued). "This association was confirmed in breast and/or ovarian cancer families and cohorts with no known BRCA1 or BRCA2 mutations, leading to the proposition to include RAD51D and RAD51C to the list of genes screened for breast cancer predisposition." (PMID 34208195, 2021). "In addition, the last V5 version of BOADICEA incorporates the effects of pathogenic variants (PVs), not only in BRCA1 and BRCA2 genes, but also in PALB2, CHEK2, ATM and BARD1 for the breast cancer model and RAD51D, RAD51C and BRIP1 for the ovarian cancer model." (PMID 35886069, 2022). "An additional 3 breast and ovarian cancer cases were not analyzed in this cohort because in additional to RAD51B germline mutations, they carried another high or moderate penetrance mutation in a cancer susceptibility gene (1 each BRCA2, RAD51D, ATM)." (PMID 34635660, 2021). "We screened for RAD51D mutations in BRCA1/2 mutation-negative index cases from 1,060 familial breast and/or ovarian cancer families (including 741 affected by breast cancer only) and in 245 unselected ovarian cancer cases." (PMID 23372765, 2013). "Similarly, in relapsed platinum-sensitive high-grade ovarian cancer patients, therapeutic responses to Rucaparib were not restricted to BRCA-mutated tumors, and were observed in several patients with mutations to other HR genes including ATM, NBN, RAD51C, and RAD51D." (PMID 35205643, 2022). "Lack of analysis on RAD51D, EPCAM and other essential hereditary ovarian cancer genes is another limitation of our study." (PMID 31472684, 2019).
breast cancer (128 papers, 2009 to 2026). A primary or metastatic malignant neoplasm involving the breast. "A RAD51D P/LP variant was identified in two patients (0.27%), one with diffuse GC at 57 years and a family history of breast cancer and another one with mixed GC at 45 years and with a GC family history." (PMID 40446793, 2025). "Eight different genes, including ATM, BRCA1, BRCA2, CHEK2, PALB2 (FANCN), RAD51C, and RAD51D, demonstrate significant correlations with an increased risk of breast cancer when harboring pathogenic variations." (PMID 40800071, 2025). "For RAD51D mutation carriers, 30.8% (4/13) of their family members have a high lifetime breast cancer risk compared to the average population, while 46% (6/13) of their siblings were in the moderate-risk category." (PMID 39202057, 2024). "Many studies have confirmed that RAD51C and RAD51D germline pathogenic variants are closely associated with the development of ovarian and breast cancer." (PMID 39206620, 2024). "While BRCA1 and BRCA2 remain the most well-known high-penetrance genes, others, such as ATM, BARD1, CHEK2, PALB2, RAD51C, and RAD51D, are now recognized as conferring moderate to high risk for breast cancer." (PMID 39590369, 2024). "Within their study, the authors recognized five TNBC predisposing genes, such as RAD51D, characterized by a cumulative lifetime risk exceeding 20% for breast cancer." (PMID 38397209, 2024). "Recent comprehensive studies have highlighted that pathogenic variants (PVs) across eight distinct genes, such as ATM, BRCA1, BRCA2, CHEK2, PALB2 (FANCN), RAD51C, and RAD51D, exhibit a substantial correlation with breast cancer risk." (PMID 38397209, 2024). "Several studies have advocated for the correlation between RAD51D GPVs and breast cancer (BC) susceptibility." (PMID 39202057, 2024). "Variants in key genes of HR, such as BRCA1, BRCA2, PALB2, BARD1, RAD51C, and RAD51D, which alter their function and/or their expression, have a significant association with breast cancer risk." (PMID 37372450, 2023). "The estimated cumulative risks of developing tubo-ovarian carcinoma and breast cancer to age 80 years were 13% (95% CI: 7–23%) and 20% (95% CI: 14–28%) for RAD51D pathogenic variant carriers." (PMID 36544182, 2022). "It’s worth noting that the frequency of RAD51D mutations was 0.38% among a large series of unselected breast cancer patients in the Chinese population which was also higher than that of the reports in Caucasian women." (PMID 36544182, 2022). "BOADICEA was extended to further incorporate the associations of pathogenic variants in BARD1, RAD51C and RAD51D with breast cancer risk." (PMID 36162851, 2022). "Our previous study showed that low frequencies of RAD51C (0.08%) and RAD51D mutations (0.73%) were identified in cohorts of breast cancers only." (PMID 35608067, 2022). "These clinical characteristics also suggested that BARD1 and RAD51D were breast cancer susceptibility genes in Chinese women." (PMID 34606182, 2021). "ATM, BARD1, CHEK2, and RAD51D were associated with a moderate risk of breast cancer with ORs ranging from 2-fold to 4-fold." (PMID 34606182, 2021). "This study classified ATM, BARD1, CHEK2, and RAD51D as moderate risk breast cancer susceptibility genes in Chinese women." (PMID 34606182, 2021). "Among these, BRCA1, BRCA2, and PALB2 were still classified as high risk, and ATM, BARD1, CHEK2, and RAD51D were still classified as moderate risk breast cancer susceptibility genes in Chinese women." (PMID 34606182, 2021). "In a cohort of 6690 families, RAD51D pathogenic variants were associated with relative risks of 7.6 and 1.83 for tubo-ovarian cancer and breast cancer, respectively." (PMID 34200360, 2021).
breast cancer (continued). "When comparing the family history of cancer, all high risk and moderate risk genes except for RAD51D were significantly associated with higher frequencies of family history of breast cancer and/or family history of any cancer." (PMID 34606182, 2021). "We demonstrated through minigene-based analysis that splicing disruptions were induced by 28 out of 37 RAD51D variants (75.7%) originally identified in breast cancer cases and/or healthy controls of the BRIDGES cohort." (PMID 34200360, 2021). "Our results indicated that BRAD1 and RAD51D were moderate risk breast cancer susceptibility genes in Chinese women." (PMID 34606182, 2021). "A recent study of multiple hereditary cancer genes identified both RAD51C [OR 1.84 (95% CI 1.28–2.71)] and RAD51D [OR 2.09 (95% CI 1.2–3.72)] as having an elevated risk of breast cancer." (PMID 33015624, 2020). "Here we have genotyped the CHEK2 mutations I157T and c.1100delC, the FANCM mutation p.Q1701X, the PALB2 mutation c.1592delT, the RAD51C mutations c.837+1G>A and c.93delG, and the RAD51D mutation c.576+1G>A in 68 male breast cancer patients." (PMID 28874143, 2017). "Although rare among familial breast cancer patients, loss of function variants in RAD51D have been associated with a relative risk of OVCA of 6.30." (PMID 28591191, 2017). "In the methylation analysis against subtype and clinical characteristics, RAD51D showed breast cancer subtype specific methylation pattern and associated with Ki67 expression level." (PMID 28424414, 2017). "These include Rad52, the human Rad51 paralogs Rad51B, Rad51C, Rad51D, Xrcc2, and Xrcc3, and breast cancer susceptibility gene Brca2." (PMID 21129202, 2010). "Significant in RAD51D-associated breast cancers; contribute to 9–20% of HRD." (PMID 40864792, 2025). "Furthermore, while recognition of RAD51C and RAD51D as OC predisposition genes has been established for several years, an association with breast cancer (BC) has only more recently been described and clinical management of this risk has been unclear." (PMID 36411032, 2023). "In addition, RAD51D germline mutation confers an increased breast cancer risk: carriers have a 20% cumulative risk of developing breast cancer by 80 years of age129,130." (PMID 35380032, 2022). "In addition, breast cancer patients with the BRAD1 and RAD51D pathogenic variants were associated with a higher frequency of family cancer history and early-onset breast cancer, respectively." (PMID 34606182, 2021). "Similarly, mutations in RAD51D were associated with increased risks of breast cancer (OR = 8.33, 95% CI 2.2−30.48, p = 0.0044)." (PMID 28649662, 2017). "Interestingly, ATM c.2289T>C (p.F763L), along with two other variants currently classified as likely benign, BRCA2 c.2926_2927delinsAT (p.S976I) and RAD51D c.251T>A (p.L84H), were determined to be associated with African American breast cancer risk when compared to ethnic-specific controls." (PMID 32866190, 2020). "Among the 8 cases with RAD51C and RAD51D mutations, 6 (75%) were triple negative breast cancer, in agreement with the recent studies suggesting that mutations in these two genes may confer higher risks of triple-negative or basal subtypes of breast cancer." (PMID 29566657, 2018). "Most breast cancer susceptibility genes are involved in the damage repair signaling pathway, i.e., including BRCA1, BRCA2, PALB2, CHEK2, ATM, BARD1, RAD51C, and RAD51D." (PMID 40649769, 2025).
breast cancer (continued). "RAD51C/RAD51D-mutated cancers and BRCA2/RAD51C hypermethylation in male breast cancer (~30% prevalence) expand PARPi candidacy]." (PMID 40864792, 2025). "For instance, beyond the well-known BRCA mutations in breast cancer, alterations in genes such as BARD1, and pathogenic variants of RAD51C and RAD51D, reported to be associated with increased breast cancer risk, have also been identified." (PMID 40723883, 2025). "Other homologous recombination DNA damage repair (HR-DDR) genes associated with breast cancer risk accounted for 15.9% (13/82) of the carriers, including ATM (n = 2), BARD1 (n = 4), CHEK2 (n = 1), PALB2 (n = 2), RAD51C (n = 1), and RAD51D (n = 3)." (PMID 38893140, 2024). "Variants involving ATM, CHEK2, BRIP1, RAD51C, RAD51D, NBN and BARD1 are known to be associated with a moderately increased risk of breast cancer and a lifetime risk of around 25%." (PMID 38439815, 2024). "According to the NCCN guidelines v2.2024 (27 September 2023), germline PVs in the genes ATM, BARD1, RAD51C, RAD51D, NF1, and CHEK2 confer an absolute breast cancer risk between 17% and 40%." (PMID 38893140, 2024). "This economic evaluation estimates the cost-effectiveness of prevention strategies for ovarian and breast cancer among individuals with pathogenic variants in cancer susceptibility genes BRCA1, BRCA2, PALB2, RAD51C, RAD51D, and BRIP1." (PMID 38334999, 2024). "How cost-effective are ovarian and breast cancer risk reduction strategies among women with pathogenic variants in individual cancer susceptibility genes (ie, BRCA1, BRCA2, PALB2, RAD51C, RAD51D, and BRIP1)?" (PMID 38334999, 2024). "Carriers of PALB2, BARD1, RAD51C, RAD51D, ATM, and CHEK2 are at higher risk of breast cancer as well." (PMID 37458761, 2023). "Several reports also demonstrated the existence of other genes at medium and low penetrance (e.g., BRIP1, RAD51C, RAD51D, BARD1, and PALB2), which have been associated with both Breast Cancer (BC) and OC risk." (PMID 35053526, 2022). "BARD1 (OR: 3.1, 95% CI: 1.3–7.2); CHEK2 (OR: 2.5, 95% CI:1.4–4.6); RAD51D (OR: 2.2, 95% CI: 1.3–3.8); and ATM (OR: 2.1, 95% CI: 1.2–3.6) were classified as moderate risk breast cancer risk genes." (PMID 34606182, 2021). "In the NCCN Guidelines® Version 1.2022, it is stated that there are not sufficient data so far to suggest preventive management of breast cancer in carriers of GPVs of RAD51C or RAD51D (RAD51C/D)." (PMID 35008774, 2021). "Similar results were found through a screening of 65,057 white woman with breast cancer where a high or moderately increased risk of disease was found in relation with pathogenic mutations in ATM, CHEK2, PALB2, and RAD51D." (PMID 34299313, 2021). "In the previous literature, germline RAD51D c.904-2A > T [NM_002878] was reported in a few cases of carcinoma, such as ovarian serous carcinoma, cholangiocarcinoma of the bile duct, and breast carcinoma." (PMID 34838098, 2021).